CD200 (CD200 molecule)
Diseases named in the same sentence as CD200 in open-access papers (continued):
Sharing a sentence is not in itself a finding about the gene and the disease.
tumor (continued). "When tumor growth was compared in WT and CD200-/- mice, the rate of growth of control EMT6 and EMT6siCD200 tumor cells was found to be similar in each strain, with EMT6siCD200 tumors consistently smaller in both WT and CD200-/- hosts at the time of sacrifice." (PMID 28234914, 2017). "Treatment of CD200-/- tumor-bearing mice by immunotherapy in combination with conventional cytotoxic chemotherapy cured primary tumors, but produced no long-lasting immunity." (PMID 28234914, 2017). "When we examined CD8+ cells in DLN of tumor-bearing CD200-/- mice, we found that metformin increased the numbers of CD8+ cells in DLN regardless of growth of control EMT6 or EMT6siCD200 tumors." (PMID 28234914, 2017). "Tumour-expressed CD200 suppresses antitumour responses, implying the potential of anti-CD200 antibodies for CD200-expressing cancers." (PMID 27212807, 2016). "Exosome cytokine proteomic profiles responses in 4THM and EMT6 tumor‐bearing mice were regulated by CD200:CD200R interactions, with attenuation of both IL‐6 and IL‐17 in 4THM CD200tg mice, and enhanced levels in 4THM CD200R1KO mice." (PMID 26725371, 2016). "CD200 has been shown to play an important role in the regulation of anti-tumor immunity, and overexpression of CD200 has been reported in a number of hematological malignancies and solid tumors as well as on cancer stem cells." (PMID 27933341, 2016). "It is also possible that the CD200+ B-cells resident at specific locations in the tumor vs. the follicles have a distinct phenotype and properties." (PMID 27462861, 2016). "RC cells had the following immunophenotype: positive for CD10, CD19, CD20, CD22, CD38, CD43, CD44, and CD79b and negative for CD3, CD4, CD5, CD8, CD11c, CD14, CD30, CD56, and CD200, which was identical to the primary tumor cells." (PMID 26515759, 2015). "In our series, preliminary data indicate a higher occurrence of myeloid-derived suppressor cells (MDSC), that are known to play a central role in regulating immune response and tumor tolerance, in CD200 positive patients." (PMID 26338961, 2015). "We have found that CD200 expression varies within different tumor types, and that specific tumor subsets also have varying expression levels of CD200." (PMID 25598973, 2014). "Since CD200 is expressed by different tumor cell types, it has recently described the relevance of the CD200-CD200R axis in cancer immune evasion." (PMID 25013764, 2014). "These experiments suggest that CD200 plays a role in suppressing the immune responses in GL261 tumor bearing mice." (PMID 25598973, 2014). "Nevertheless, we demonstrate the potential importance of CD200 in tumor immunotherapy and the use of antagonist peptides as effective agents to block the suppressive effects of sCD200." (PMID 25598973, 2014). "Protection (in CD200KO or CD200R1KO mice) was not related to a direct immune response from recipient mice to CD200 expressed on tumor cells themselves." (PMID 25409195, 2014). "Tumor-bearing mice treated with the CD200 antagonist one day prior to and concurrently with OVA vaccine had increased numbers of SIINFEKL-specific CD8 T-cells compared to mice vaccinated without the antagonist (p < 0.01)." (PMID 25598973, 2014). "B7H1 and B7H4 overexpression is associated with inhibition of the immune system in many solid tumors, and altogether with CD200 molecule plays an important role in tumor invasion by promoting malignant transformation." (PMID 23632869, 2013). "Signals delivered through the CD200:CD200R axis have been shown to play an important role in the regulation of anti-tumor immunity." (PMID 23632869, 2013). "To examine the impact of CD200 expression on tumor formation and growth, we injected B16.OVA.CD200 or B16.OVA.Ctrl cells into C57BL/6 mice subcutaneously (s.c.)." (PMID 22319630, 2012). "To understand if CD200-mediated inhibition of tumor formation and metastasis observed in C57BL/6 mice were due to stimulation of adaptive immunity, we did similar experiments in Rag1−/− C57BL/6 mice." (PMID 22319630, 2012).
tumor (continued). "Cytokine levels were consistently lower in cultures containing CD200-positive tumor cells, while CD200 blockade using an anti-CD200 antibody abrogated the suppression of cytokine production." (PMID 22319630, 2012). "In contrast to our observation, CD200 induction on tumor cells was recently shown to correlate with more tumor metastasis." (PMID 22319630, 2012). "CD200 is only expressed in some lineage of tumors, while CD200R is expressed in tumor associated myeloid cells essentially in all solid tumors; thus, targeting CD200R should have broader implication in the treatment of cancer." (PMID 22319630, 2012). "We have recently demonstrated that tumor associated myeloid cells express high levels of CD200R, and they are susceptible to CD200-mediated inhibition." (PMID 22319630, 2012). "The lung weight and number of tumor foci in the lungs of anti-Gr1 treated mice were similar to the mice that only received B16.OVA.CD200." (PMID 22319630, 2012). "Expression of CD200 significantly inhibited tumor formation and growth, and promoted survival of tumor bearing mice." (PMID 22319630, 2012). "In this study, we have compiled evidence that tumor expressed CD200 can directly interact with myeloid cells to inhibit tumor formation and metastasis in a CD200R-dependent manner." (PMID 22319630, 2012). "The tumor volumes of T cell-treated CD200-positive tumors were significantly smaller and the survival times of mice with CD200-positive tumors were significantly longer compared to mice with CD200-negtive tumors receiving the same T cell treatment." (PMID 22319630, 2012). "To determine if tumor cell expression of CD200 directly inhibits the functions of Gr1+ myeloid cells, we purified Gr1+ cells from spleens or lungs using MACS beads." (PMID 22319630, 2012). "The trend for clinical benefit in participants with tumor CD200 expression suggests that 23ME-00610 inhibits CD200R1 signaling and may reverse CD200-mediated immune evasion." (PMID 39651931, 2025). "Serum levels of soluble CD200 may also be a biomarker that predicts tumor regrowth prior to the radiologic appearance of tumor." (PMID 39958231, 2025). "Interestingly, our findings also indicate that RIDα/β overexpression in adipocytes promotes an immunosuppressive tumor microenvironment through upregulation of Ido1, Mrc1, and Cd200." (PMID 40526430, 2025). "Thus, further exploration of CD200 tumor expression as a potential predictive biomarker for 23ME-00610 clinical benefit is planned." (PMID 39651931, 2025). "Importantly, the MFP of PyMT-RIDad mice also exhibited an enrichment of immunoregulatory molecules such as Ido1, Mrc1, and Cd200, suggesting a shift toward a generally immunosuppressive tumor microenvironment." (PMID 40526430, 2025). "Analysis of participant tumors suggested that patients with high tumor CD200 expression may be more likely to have clinical benefit with CD200R1 inhibition, which suggests promise as a predictive biomarker for efficacy." (PMID 39651931, 2025). "Notably, CD200 was found to be upregulated in several types of tumor cells as compared to their normal tissue counterparts." (PMID 41233805, 2025). "Interestingly, CD200R−/− mice receiving CD200+ B16 cancer cells showed striking tumor growth in multiple organs, while the growth of the same tumor in wild-type mice was limited." (PMID 40075669, 2025). "Moreover, studies have shown that different CD200 genotypes have different prognostic effects on tumor patients." (PMID 40718780, 2025). "This suggests that CD200 may play a completely different role outside of NB cells than in the tumor cells themselves." (PMID 40718780, 2025). "Future studies should be directed to develop inhibitors that could block the interaction of CD200 with its receptor and, at the same time, be able to deliver a cytotoxic drug directly to the tumor itself." (PMID 39795972, 2024). "CD200 expression was significantly decreased on tumor cells in grade 3 tumors." (PMID 38619621, 2024).
tumor (continued). "This examines complementary mechanisms since anti-CD200 therapies deplete immunosuppressive signals within the tumor microenvironment and amplify immune-mediated tumor attacks, while CDK4/6 inhibitors block tumor proliferation via the induction of G1 cell cycle arrest." (PMID 39795972, 2024). "CD200 promotes an immunosuppressive environment and contributes to tumor immune escape." (PMID 39795972, 2024). "CD200 expression may support tumor growth and modify the composition of tumor-draining lymph nodes, one of the important components, locally, of any immune landscape." (PMID 39795972, 2024). "CD200 is expressed by many cell types, including tumor cells." (PMID 39795972, 2024). "CD200 in tumor cells suppress antitumor responses by facilitating immune evasion." (PMID 39795972, 2024). "We hypothesize that CD200 protein and mRNA transcripts are upregulated by the tumor and stroma cells in the PDAC TME." (PMID 38619621, 2024). "It is acknowledged that the expression of CD200 can play a pro-tumorigenic role in various malignant tumors, both hematopoietic and solid tumors, often through indirect effects mediated by an altered tumor microenvironment (TME)." (PMID 38540350, 2024). "The role of CD200 in cancer immunotherapy could augment the immune system and modulate its typical function toward the tumor antigens." (PMID 39795972, 2024). "However, exactly which stromal and tumor populations in the pancreatic TME express CD200 has yet to be determined." (PMID 38619621, 2024). "We previously reported that CD200 is elevated in PDAC, and we hypothesized that CD200 was overexpressed on both tumor and stromal cells in the pancreatic TME." (PMID 38619621, 2024). "Genetic factors also influence the level of CD200 and impact tumor growth and dissemination." (PMID 39795972, 2024). "Indirectly, CD200 promotes tumor growth by making the environment favorable for tumor development." (PMID 39795972, 2024). "The infusion of blocking anti-CD200 antibody to MCC xenograft mice led to increased targeting to the tumor, which the authors suggested might portend a novel immunotherapy for MCC, independent of the PD-1/PD-L1 blockade." (PMID 38540350, 2024). "More recently, the notion that altered tumor growth might depend on the relative affinities of the interaction (in the TME) between CD200 and CD200R expressed on M2-type macrophages compared with those on M1-type macrophages has been raised." (PMID 38540350, 2024). "Moreover, vaccines targeting CD200 have been shown to increase, in preclinical studies, the immune responses against CD200-expressing tumor cells, improve immune detection, and effectively killing the cancer cells." (PMID 39795972, 2024). "Future analyses using newer techniques such as spatial transcriptomics could provide valuable information to the function of these CD200 + cell types and their interactions in the tumor." (PMID 38619621, 2024). "Preliminary studies show that blocking CD200 improves the immune response and delays tumor growth." (PMID 39795972, 2024). "Graphical Abstract: We identified a novel population of CD4 tumour‐infiltrating lymphocytes (TILs) in BLCA, defined as the co‐expression of PD‐1 and CD200, which may help to explore the mechanisms of tumour progression and immunotherapy resistance." (PMID 37313656, 2023). "Further investigation of CD200R-blocking antibodies in tumours expressing high levels of CD200 could be warranted." (PMID 37082107, 2023). "Aside from its role in suppressing anti-tumor immunity, the CD200/CD200R axis has also been hypothesized to mediate cancer invasion and metastasis by facilitating the remodeling and degradation of extracellular matrix proteins." (PMID 38137547, 2023). "Moreover, as demonstrated by several correlational studies, the frequency and tumor infiltration of Tregs significantly positively correlates with CD200 expression, which indicates a pathophysiologic link between CD200 activity and Treg induction." (PMID 38137547, 2023).
tumor (continued). "However, further research is necessary to fully understand the complex interactions of CD200 in the tumor microenvironment and to optimize its therapeutic potential in cancer immunotherapy." (PMID 38137547, 2023). "CD200 expression on human cancer cells is believed to confer a pro-tumorigenic role in cancer development by fostering the formation of an immunosuppressive tumor microenvironment." (PMID 38137547, 2023). "Notably, the immune checkpoint molecules CD24 and CD200 have garnered attention owing to their involvement in tumor immune evasion." (PMID 37894750, 2023). "Additionally, it was found that the supernatant derived from the SCC tumor effectively induced the expression of CD200 on human dermal blood endothelial cells in vitro." (PMID 36756156, 2023). "In addition, adenovirus-expressing soluble CD200R-Ig eliminated the pro-tumor effects of CD200, including the induction of M2-like polarization, increased recruitment of regulatory T cells, and decreased the number of CD8+ T cells." (PMID 37894750, 2023). "CD200 is an immunoregulatory cell surface ligand with proven pro-tumorigenic credentials via its ability to suppress CD200 receptor (CD200R)-expressing anti-tumor immune function." (PMID 36738455, 2023). "As such, these research findings suggest yet another tumor-promoting mechanism of CD200." (PMID 38137547, 2023). "In addition to tumor cells within the TME, CD200 is also predominantly found on T cells and the endothelial cells lining tumor-nourishing blood vessels." (PMID 36756156, 2023). "Of note, recent studies suggest that CD200-CD200 receptor (CD200R) interaction might be essential in controlling the myeloid heterogeneity in tumours by a mechanism involving CD200-expressing endothelial cells." (PMID 36161514, 2023). "Simultaneously blocking other immune checkpoint molecules, such as CTLA-4, PD-1, and Tim-3, in addition to CD200 may synergistically boost anti-tumor activity." (PMID 36756156, 2023). "In the future, unbiased genomic- and proteomic-based approaches may help to clarify these issues by identifying tumor-specific mechanisms of CD200 expression regulation across a variety of human cancers that may be leveraged for broader therapeutic benefit." (PMID 36738455, 2023). "The bidirectional role of CD200 may be attributed to the inflammatory microenvironment of the specific tumor." (PMID 38137547, 2023). "However, CD200 expression was induced in poorly-differentiated primary and metastatic cSCC with enrichment of CD200 localized to leading edge tumor cells." (PMID 36738455, 2023). "Nonetheless, macrophage amplification in LNs—for instance, via an induction of podoplanin expression in LECs or via blockade of CD200 or BST2—could help to activate endogenous as well as vaccine-induced tumor immunity." (PMID 35892863, 2022). "Substantial numbers of VEGF-C+ CD68+ CD163+ TAMs were distributed in the lesional skin of Merkel cell carcinoma, and expression of CD200 in tumor cells induces immunosuppressive CD163+ CD200R+ M2 TAMs and Foxp3+ Tregs to maintain the immunosuppressive tumor microenvironment." (PMID 35409404, 2022). "In addition, ADAM28 induces the shedding of soluble CD200 in B cells, which delivers immunomodulatory signals to suppress T cell-mediated anti-tumor responses." (PMID 35634306, 2022). "In addition, recent findings illustrate a clear correlation between the expression of CD200 on MM PCs and the frequency of immunosuppressive Treg cells involved in the enhancement of tumor growth and chemoresistance." (PMID 36499093, 2022). "Thus, it is critical to understand the potential impacts of CD200 blockade in a more human relevant tumor model." (PMID 34692697, 2021). "Additionally, we measure the expression of CD200 in both the tumor and stromal compartments of patients in the same cohort." (PMID 34771664, 2021).
tumor (continued). "Neither tumor nor stromal expression of CD200 or CD200R demonstrated significant associations with epidermal growth factor receptor (EGFR) or KRAS mutation status in NSCLC patients." (PMID 33804482, 2021). "MDSCs were also found in advanced stages of SCC; these cells express high levels of CD200R+ that may interact with CD200+ tumor cells conferring immune privilege and favoring metastasis development." (PMID 33634137, 2021). "Once again, levels of a soluble form CD200, sCD200, rose in animals with progressive tumor growth." (PMID 33562512, 2021). "CD200+ tumor cells abolish the ability of PBMCs to eradicate tumor cells." (PMID 33562512, 2021). "The R2 value for CD200 expression in the tumor versus stromal compartment of patients was 0.63." (PMID 34771664, 2021). "Likewise, the patients’ tumor specimens were compared by CD200 stromal compartment scores across blocks of YTMA454." (PMID 34771664, 2021). "A good correlation between tumor and stromal expression of CD200 (R2 = 0.69) was noted as well." (PMID 33804482, 2021). "Increased expression of CD200 in tumor was associated with female sex, never-smoking status, adenocarcinoma histology, early disease stage, and EGFR mutations." (PMID 33804482, 2021). "Thus, our data suggests that anti-CD200 therapy alters tumor microenvironment through similar mechanisms observed in CD200R–/– mice." (PMID 34692697, 2021). "These opposite results suggest that the effect of CD200 depends on the tumor stage and type." (PMID 33860055, 2021). "Moreover, interaction of CD200 with CD200R has also been reported to play a role in the regulation of tumor immunity." (PMID 33324560, 2020). "Indeed, the binding of CD200 on tumor cells with its receptor (CD200R) expressed on T lymphocytes can induce a switch from an antitumor T helper (Th)-1 to an immunosuppressive Th-2 response." (PMID 32120774, 2020). "CD200 is required to maintain bone marrow cell homeostasis; however, it may cause exacerbation due to increased MDSC infiltration during tumor growth." (PMID 32707672, 2020). "Moreover, treatment with anti-CD200 monoclonal antibodies (Abs) was also highly effective in this model and inhibited the growth of Namalwa CD200 tumor cells in NOD/SCID hu-mice by >90%." (PMID 33324560, 2020). "Examination of cluster-specific marker genes showed that tumor ECs expressed a unique set of genes such as Col18a1 and Aplnr, but also shared a number of expressed genes with venous ECs, especially with PV, such as Cd63, Ehd4, and Cd200." (PMID 32440964, 2020). "Therefore, combination of a CD200 synthetic peptide that leads to production of anti-CD200 antibodies in the organism and inhibits MDSCs with a tumor vaccine has been developed." (PMID 32707672, 2020). "This tumor model clearly demonstrated the immunosuppressive activity of CD200." (PMID 33324560, 2020). "The diffuse and strong immunoreactivity of CD200 in SPNs may provide some insights into the biology of this peculiar tumor entity." (PMID 30132130, 2019). "CD200 expression has been documented in different tumor types, like colorectal and ovarian cancers." (PMID 30132130, 2019). "Dogs receiving the canine-specific CD200-directed inhibitor and the autologous tumor lysate had significanlty longer survivals (median 12.7 months) compared to a historical control group of dogs treated with surgery and autologous tumor lysate (median 6.4 months)." (PMID 31788444, 2019). "Through this endogenous inhibitory pathway, CD200:CD200R1 interaction may also be featured in tumor progression, outgrowth, and/or metastasis." (PMID 30800162, 2019). "Indeed, we reported CD200 in tumor lysates compromises the ability of local APCs to initiate an adaptive immune response to tumor-specific antigens." (PMID 30682795, 2019).